IL1B (interleukin 1 beta)
Diseases named in the same sentence as IL1B in open-access papers (continued):
Sharing a sentence is not in itself a finding about the gene and the disease.
respiratory infections (20 papers, 2009 to 2026). "Thus we hypothesized that respiratory infections causes the release of EVs in the airway and that the raised ATP levels, present in respiratory disease, triggers the release of IL-1β/IL-18, neutrophilia and subsequent disease exacerbations." (PMID 24972036, 2014). "Research has shown that IL-1β plays a major role in the acute inflammatory response of respiratory infections and promotes the elimination of pathogens." (PMID 37735372, 2023). "This study observed that EVs released during respiratory infections carried and released IL-1b and IL-18, suggesting a mechanism that results in disease exacerbation." (PMID 35382831, 2022). "Reports of IL1β involvement in chlamydial infections have been demonstrated in both Chlamydia pneumoniae and Chlamydia muridarum mouse respiratory infections." (PMID 31415633, 2019). "This is relevant in the context of P. aeruginosa respiratory infections as it has been demonstrated in murine acute P. aeruginosa pneumonia models that IL-1β and IL-18 released upon alveolar macrophage inflammasome activation are deleterious for the host." (PMID 25706389, 2015). "IL-1β levels are enhanced in PwCF harboring these SNPs compared to patients without them, and IL-1β-mediated inflammation is further increased in the presence of respiratory infection." (PMID 40791588, 2025). "Relevant for the current review are previous observations suggesting a reduced risk for respiratory infections with the MeD and especially a reduced risk of inflammation, with a decrease in C-reactive protein (CRP) and pro-inflammatory cytokines, such as interleukin (IL)-6 and IL-1β." (PMID 37048015, 2023). "In addition, respiratory infection, whether viral or bacterial, may be responsible for periods of exacerbations, as they drive an increased release of functional EVs which contain pro-inflammatory cytokines IL-1B and IL-18 and result in exacerbated neutrophilia." (PMID 35382831, 2022). "Respiratory infection with the attenuated Live Vaccine Strain (LVS) and the highly virulent SchuS4 strain of Ft engenders intense peribronchiolar and perivascular inflammation, but fails to elicit select pro-inflammatory mediators (e.g., TNF, IL-1β, IL-6, IL-12, and IFN-γ) within the first ∼72 h." (PMID 23554897, 2013). "Moreover, in vivo studies with respiratory infection of Staphylococcus aureus have demonstrated that neutralization of NLRP3 improves bacterial clearance, while blocking IL-1β/IL-18 does not." (PMID 36068223, 2022).
apical periodontitis (19 papers, 2016 to 2025). "For example, SNPs in interleukin genes, such as IL-1β (-511 C/T), have been linked to an increased risk of apical periodontitis, while MMP gene polymorphisms contribute to tissue degradation in periapical lesions." (PMID 39723289, 2024). "Increased IL-1β production in periapical periodontitis may be associated with the activation of NLRP3 and AIM2 inflammasomes." (PMID 34177950, 2021). "In addition, estrogen deficiency can induce activation of the NLRP3/caspase-1/IL-1β axis and aggravate periapical bone loss in postmenopausal patients and ovariectomized rats with periapical periodontitis." (PMID 34177950, 2021). "Multiple studies have investigated the polymorphisms of various ILs, including IL-1α, IL-1β, IL-6, TNF-α, IL-8, IL-10, and IL-12, and their association with the occurrence of apical periodontitis." (PMID 39723289, 2024). "Cytokines such as IL-1α, IL-1β, IL-6, IL-8, and IL-12p40 play significant roles in the development of apical periodontitis." (PMID 39723289, 2024). "Immunohistochemical staining demonstrated a higher expression of IL-1β and IL-10 in apical periodontitis." (PMID 38612664, 2024). "Butyrate combined with lipoteichoic acid significantly increased caspase-1 activation and IL-1β secretion both in vitro and in vivo in a rat model of apical periodontitis." (PMID 37893122, 2023). "The inflammasome activation and IL-1β expression are increased in periapical lesions with apical periodontitis." (PMID 36977666, 2023). "SCFAs and Ef.LTA synergistically induced the inflammasome activation and IL-1β expression in macrophages and rat apical periodontitis models." (PMID 36977666, 2023). "IL-1α and IL-1β, released by macrophages, lymphocytes, and dendritic cells, are two pro-inflammatory cytokines that play a significant role in developing and progressing apical periodontitis by activating osteoclasts and promoting bone resorption." (PMID 38956025, 2024). "Furthermore, Ef.LTA and butyrate synergistically induced the pulp necrosis that accompanies IL-1β expression in the rat apical periodontitis model." (PMID 36977666, 2023). "Collectively, IL-1β and the inflammasome might be used as molecular targets for apical periodontitis." (PMID 36977666, 2023). "Thus, we examined the effect of Ef.LTA and butyrate on IL-1β expression in vivo using the previously established rat apical periodontitis model." (PMID 36977666, 2023). "IL-1β might also play a role in the initiation and up-regulation of the inflammatory response in apical periodontitis by increasing the levels of IL-6 and prostaglandin E2 production." (PMID 30012121, 2018). "Apical calculus may induce IL-1β release in human macrophages, and these deposits in periapical tissues may sustain apical periodontitis lesions indefinitely." (PMID 27632566, 2016). "Additionally, the presence of at least one polymorphic T allele in IL-1β increases the risk of persistent apical periodontitis by sevenfold compared to individuals without the polymorphism." (PMID 39723289, 2024). "CH demonstrated significant microbial reduction (up to 99.5%), decreased inflammatory mediators (IL-1β, TNF-α), and enhanced tissue healing, making it a reliable choice for managing apical periodontitis." (PMID 41438829, 2025). "Several studies have confirmed the pro-inflammatory nature of periapical granulomas, noting higher levels of IL-1β, IL-6, TNF-α, and IL-17 in patients with symptomatic apical periodontitis compared to those with asymptomatic cases." (PMID 39723289, 2024). "We showed that Ef.LTA/butyrate efficiently induced IL-1β in PMA-differentiated THP-1 cells and apical lesions in rats with apical periodontitis." (PMID 36977666, 2023). "The increased IL-1β and caspase-1 expression by Ef.LTA/butyrate was confirmed in the rat apical periodontitis model." (PMID 36977666, 2023).
apical periodontitis (continued). "Therefore, this study evaluated the immunoexpression of IL-1β, TNF-α, and IL-17 in apical periodontitis from type 2 diabetic patients through immunohistochemistry." (PMID 36819640, 2023).
Chagas disease (19 papers, 2014 to 2026). A parasitic infection caused by Trypanosoma cruzi. "Indeed, IL-6 has a critical role in regulating inflammasome activation and IL-1β-induced NO production early after pathogen encounter in a murine model of T. cruzi infection (the causal agent of Chagas disease)." (PMID 37818368, 2023). "The progression of Chagas disease involves cellular death and the release of proinflammatory cytokines, such as IL‐1β, both of which are critical for elucidating the immunopathological mechanisms underlying this condition." (PMID 41573114, 2026). "Here, we assessed the role of IL-1β in ventricular and electrical function during the chronic stage of Chagas disease." (PMID 36341442, 2022). "Due this dichotomous characteristic in the activation of IL-1β in patients with different clinical forms of Chagas' disease, we propose MMP-2 and MMP-9 as potential biomarkers of prognostic which should be better investigated." (PMID 31057540, 2019). "Our data suggest that different IL-1β activation pathways are clearly involved in the chronic phase of Chagas disease." (PMID 31057540, 2019). "Our data propose for the first time a distinct molecular mechanisms for the production of IL-1β in patients with different clinical forms of Chagas disease." (PMID 31057540, 2019). "The expression of IL-1β was significantly higher in neutrophils from patients with Chagas disease compared to NI group, before and after in vitro stimulation." (PMID 28118356, 2017). "The expressions of different cytokines (IL-10, IFN-γ, TNF-α, IL-6, IL-1β) were evaluated in the plasma of healthy individuals and patients with different forms of Chagas disease." (PMID 24603474, 2014). "Although preclinical studies have linked P2X7 receptor activation to inflammasome assembly, IL‐1β release, thymocyte loss, and cardiac inflammation in Trypanosoma cruzi infection models, its precise role in human disease is not clarified." (PMID 41573114, 2026). "Since in Chagas disease the IL-1β levels are increased, as we also observed here, we tested the hypothesis that anakinra would reverse the electrical disturbances induced by T. cruzi infection in a well-established CCC model." (PMID 36341442, 2022). "We showed association between the IL1B −31 TC genotype and lower NYHA in Chagas disease." (PMID 33193300, 2020). "During Trypanosoma cruzi infection, the immune system activates a robust inflammatory response, involving cytokines and chemokines like IFN-γ, TNF, IL-6, IL-1β, CCL2, and CCL5, to control parasite replication." (PMID 40936920, 2025). "There are currently no works systematically approaching the role of IL-1β in controlling established heart parasitism at the chronic stage of Chagas disease." (PMID 36341442, 2022). "Our results demonstrated that Chagas disease patients had higher serum levels of CXCL9, CXCL10 and IL-1β and lower serum levels of CCL5 than non-infected subjects." (PMID 32393333, 2020). "In our cohort of chronically infected Chagas disease patients, those with detectable T. cruzi parasitemia measured through RT-PCR in peripheral blood had a higher concentration of pro-inflammatory cytokines (TNF-α, IL-1β, IL-6 and IL-17A) and IL-4 than those with negative RT-PCR." (PMID 38133693, 2023).
cyst (19 papers, 2014 to 2026). A sac-like closed membranous structure that may be empty or contain fluid or amorphous material. "The interplay of pro-inflammatory and anti-inflammatory mediators in ADPKD highlights a complex immune environment, where cytokines like IL-1β, IL-6, and IL-37 play key roles in cyst formation and inflammation regulation." (PMID 41431718, 2026). "Several research groups have investigated the level of IL‐1B protein in the cyst fluid of IPMNs as a potential marker of malignancy; however, the results are controversial." (PMID 39969214, 2025). "IPMN is also often associated with chronic pancreatitis and some studies have found an elevated IL‐1B level in cyst fluid compared to other pancreatic cystic neoplasms." (PMID 39969214, 2025). "Cyst levels of Ngal, IL-1β and glucose showed statistically significant differences between patients with pseudocysts compared to those with cyst neoplasm." (PMID 38542201, 2024). "The levels of IFN-γ, IL-1β, IL-2, IL-4, IL-10, IL-12, and IL-13, in contrast, were significantly higher in pus than in cyst fluid." (PMID 35965529, 2022). "In previous studies, ADPKD cyst nephrons were shown to have elevated transcript expression of a number of inflammasome components, including IL-1β and IL-18." (PMID 36523654, 2022). "To further evaluate inflammasome activation in the kidneys of ADPKD patients, we measured the levels of IL-1β and IL-18, which are primary products of activated Caspase-1, in the cyst fluids collected from 12 different patients." (PMID 36523654, 2022). "On the other hand, IL-1α and IL-1β levels in the cyst group were as low as those in the control group in the present study." (PMID 30012121, 2018). "Since P2X7 activation co-stimulates formation of the NALP inflammasome, cystic epithelial cells may be the primary sources of the IL18 and IL1β identified in cyst fluid." (PMID 27871310, 2016). "Other authors reported about the identification of high-risk/malignant lesions by examination of the cyst fluid of IPMNs either by analyzing the MUC expression and cyst fluid cytokine levels (e.g., interleukin-1 beta) or by recognition of atypical cell components." (PMID 24783207, 2014). "This study is the first to show that LPS, TNF-α and IL-1β increase the production and secretion of LTB4 and cyst-LTs by the pig endometrial stromal cells." (PMID 39843578, 2025). "Combining cyst fluid PGE2, IL-1β, and serum CA 19-9 optimizes specificity and positive predictive value (PPV) for high-grade dysplasia (HGD)/invasive IPMN." (PMID 41181742, 2025). "Proinflammatory cytokines IL-1β, TNF-α, and IL-2 were identified in the cyst fluid of human APKD kidneys." (PMID 39768851, 2024). "For cyst type CE3 in Year 3, levels of IL-17A, IL-8, IL-1β, MIP-1α and MIP-1β were slightly elevated relative to those in CE4 in Year 2 whereas IL-2, TNF-α, IL-1Rα and G-CSF maintained stable levels." (PMID 32171321, 2020). "After 16 days of culture, organoids clearly showed a cyst-like morphology rather than a typical alveolosphere morphology in the IL-1β group, which was also reflected by the quantification of organoid diameter (285.08 μm ± 11.6 μm vs. 145.04 μm ± 9.16 μm)." (PMID 38891054, 2024). "In this study, we had not systematically investigated the effects of iron on macrophage polarization, but we found there were higher expressions of IL8 and VEGF, lower expressions of TNFα and CCL2, and no change in IL1b and IL6 in the macrophages treated with cyst fluid and iron." (PMID 36547083, 2022).
esophageal cancer (19 papers, 2016 to 2026). A primary or metastatic malignant neoplasm involving the esophagus. "The link between inflammation and esophageal cancer is well-established; in particular, interleukin (IL)-1β is overexpressed in Barrett’s esophagus, and polymorphisms in the IL-1β gene are associated with Barrett’s esophagus." (PMID 33671768, 2021). "IL-1β is up-regulated in breast, colon, lung, oral, and esophageal cancers, and linked to poor prognosis for patients with esophageal cancer." (PMID 35821823, 2022). "IL-1β is also a prognostic factor in various cancers, including lung, breast, colon, gastric, and esophageal cancers." (PMID 38580797, 2024). "The pro-cancer effects of IL-1β have been widely demonstrated, but few studies have been reported on the oncogenic mechanisms of IL-1β in esophageal cancer." (PMID 38762529, 2024). "In this study, the expression of IL-1β in esophageal cancer was first preliminarily analyzed using the TIMER, GEPIA, and UALCAN databases." (PMID 38762529, 2024). "As shown, the expression of IL-1β in esophageal cancer was significantly higher than that in normal tissues (P < 0.05)." (PMID 38762529, 2024). "The expression of proinflammatory M1 macrophage genes such as IL1β and TNFα were significantly downregulated in esophageal carcinoma tissues, while M2 marker genes TGFβ1 and MRC1 were upregulated." (PMID 34612767, 2021). "In contrast to IL-1α and IL-1β which promotes inflammation, IL-1RA has been demonstrated to suppress angiogenesis accompanying gastric and esophageal cancer cell growth." (PMID 32408627, 2020). "We also showed distinct systemic cytokine signatures in gastric and esophageal cancers and their benign conditions, with cytokine panels consisting of IL-1β/IL-1ra/IL-6/RANTES or IL-1β/IL-6/IL-4/IL-13 holding promise as differential biomarkers in GC." (PMID 32630408, 2020). "Additionally, including IL-1β and IL-6 and TNF-α have been linked also with the pathogenesis of esophageal cancer." (PMID 34830880, 2021). "While the pro-inflammatory cytokine IL-1β has been known to contribute to the development of various types of tumors, its role in regulating esophageal cancer progression has not been extensively studied." (PMID 38762529, 2024). "In esophageal carcinoma, IL8 and IL1β are the main downstream effectors of NF-κB40." (PMID 33574243, 2021).
familial cold autoinflammatory syndrome (19 papers, 2015 to 2025). Familial cold urticaria (FCAS) is the mildest form of cryopyrin-associated periodic syndrome (CAPS) and is characterized by recurrent episodes of urticaria-like skin rash triggered by exposure to cold associated with low-grade fever, general malaise, eye redness and arthralgia/myalgia. "Studies have shown that familial cold autoinflammatory syndrome and Muckle–Wells syndrome, which are characterized by the excessive inflammatory response in various organs, are caused by increased IL-1β secretion." (PMID 32595732, 2020). "The alteration of NLRP3 genetic coding of cryopyrin protein manifests at a higher number of active IL-1β production, which leads to familial cold autoinflammatory syndrome, Muckle–Well syndrome and neonatal-onset multisystem inflammatory disease." (PMID 35528818, 2022). "Additionally, familial cold autoinflammatory syndrome (FCAS) in one Japanese family was found to be due to a missense mutation in NLRC4 causing enhanced activation of caspase-1 along with increased production of IL-1β." (PMID 33494299, 2021). "CAPS is induced by uncontrolled IL-1β release and has three main clinical phenotypes: familial cold autoinflammatory syndrome (FCAS), Muckle–Wells syndrome (MWS), and neonatal-onset-multisystem inflammatory disease (NOMID)." (PMID 37443800, 2023). "Familial cold autoinflammatory syndrome (FCAS) represents the mildest form of the disease, characterized by cold‐induced inflammation and IL‐1β production." (PMID 39327931, 2025). "Rilonacept is an IL-1 receptor fusion protein consisting of the Fc portion of human IgG1 and the human IL-1 receptor which traps both IL-1α and IL-1β, and clinically used for familial cold autoinflammatory syndrome (FCAS), Muckle–Wells syndrome (MWS), and recurrent pericarditis." (PMID 37881433, 2023). "Familial cold autoinflammatory syndrome, the mildest form of CAPS, is characterized by cold-induced inflammation induced by the overproduction of IL-1β." (PMID 35616535, 2022). "Abnormal NLRP3 inflammasome activation and excessive IL-1β secretion is the major reason of CAPS, and has been demonstrated in three clinical subtypes: neonatal-onset multisystem inflammatory disease (NOMID), Muckle-Wells syndrome (MWS), and familial cold autoinflammatory syndrome (FCAS)." (PMID 36891515, 2023).
juvenile idiopathic arthritis (19 papers, 2012 to 2026). Juvenile idiopathic arthritis (JIA) is the term used to describe a group of inflammatory articular disorders of unknown cause that begin before the age of 16 and last over 6 weeks. "In juvenile idiopathic arthritis (JIA), excessive production of IL-6 and IL-1β (for systemic JIA) has been implicated in their pathogenesis." (PMID 25344730, 2014). "IL-1β-positive MVs were also detected in plasma from patients with systemic juvenile idiopathic arthritis." (PMID 38655252, 2024). "Amongst various IL-1 polymorphisms, IL-1β-511C/T promoter has shown promising susceptibility in the progression of inflammatory disorders such as RA and SLE and juvenile idiopathic arthritis as well; however, evidence on the association with CCS is still lacking." (PMID 37371064, 2023). "Moreover, canakinumab (Ilaris®), is a monoclonal antibody targeting IL-1β which has demonstrated efficacy in the treatment of systemic onset juvenile idiopathic arthritis (So-JIA)." (PMID 31231388, 2019). "In juvenile idiopathic arthritis (JIA), the most common rheumatoid disorder in pediatrics, an elevation of proinflammatory cytokines, such as IL-1β, IL-6, IL-8, or TNF-α, has been demonstrated in both the serum and synovial fluid of patients with JIA." (PMID 31118902, 2019). "As in juvenile idiopathic arthritis, an autoinflammatory-mediated disease, IL-1β also seems to play a strategic role in SARS-CoV-2 infection, by activating the NLRP3 inflammasome, as documented by the increased IL-1β levels in lymphocytes and in the sera of infected patients." (PMID 32397684, 2020).